CD4 (CD4 molecule)
Diseases named in the same sentence as CD4 in open-access papers (continued):
Sharing a sentence is not in itself a finding about the gene and the disease.
viral infection (continued). "Lymphocytopenia and CD4+ T lymphocytopenia can be associated with many bacterial, fungal, parasite and viral infections." (PMID 24893304, 2012). "Depletion of mature CD4+ T cells, deficiency in cell-mediated immune responses, increased susceptibility to viral infections." (PMID 22905720, 2012). "The only factor associated with a CXCR4-using virus infection in multivariate analysis was the nadir of CD4 cells: <200/mm3 (OR: 3.94, 95%CI: 1.39–11.14)." (PMID 23226258, 2012). "In chronic viral infection, CD4 depletion results in loss of long-term CD8 T cell responses, and host animals maintain high viral loads." (PMID 22912696, 2012). "Combined, these findings provide additional evidence that intestinal CD4+ T cells are highly susceptible targets for viral infection and lysis in early infection, and that activated CD4+ T cells are selectively depleted in primary infection." (PMID 22096538, 2011). "This shows that low CD4+ T lymphocyte counts are associated with a variety of conditions in viral infections." (PMID 21605420, 2011). "Differences in the exposure to other viral infections than HIV is an unlikely cause of the deviations observed in the CD4+ and CD8+ T cell compartments in these individuals." (PMID 22177276, 2011). "We further hypothesized that the increased proliferation of Pank4-deficient CD4+ T cells could play an improved protective role in a mouse model of virus infection." (PMID 40962808, 2025). "A decrease in CD3+ and CD3 + CD4 + lymphocytes may indicate an impaired immune response, making the patients more susceptible to severe viral infection and less able to clear the virus." (PMID 41187212, 2025). "When a causative drug is administered during an ongoing viral infection, increased infiltration of inflammatory CD4+ and CD8+ T-cells into the skin may lead to enhanced production of inflammatory cytokines such as IL-8 and IL-36, potentially triggering AGEP." (PMID 40125151, 2025). "Moreover, IL-10 contributes to memory CD4+ T cell homeostasis and has been linked to the prolonged persistence of CD4+ T cells in the central nervous system during viral infections." (PMID 39697333, 2024). "The negative association between TNF-α and PD-1 expression on CD3+/CD4+ T cells further supports the notion that diabetes-induced immune alterations could diminish the T cell response, potentially exacerbating viral infections." (PMID 39456722, 2024). "JAK inhibitors also impair natural killer cell function and CD4-lymphocytes, which could also explain the increased risk of viral infections, including HHV-8." (PMID 37693927, 2023). "Consistent with previous studies, intact proviruses were readily detected in lymph nodes; moreover, we detected relatively high frequencies of intact proviruses in the colon, likely reflecting viral infection of CD4 T cells residing in gut-associated lymphoid tissues (GALT)." (PMID 37938115, 2023). "The developed technique showed that CD4 + T cell surface glycosylation could influence the susceptibility of CD4 + T cells to viral infection." (PMID 38014012, 2023). "Therefore, studies of the interactions between HIV-infected Mø and DCs with CD4+ T lymphocytes are important to elucidate the mechanisms underlying the interactions leading to viral infection of these cells." (PMID 37243118, 2023). "The CD4/CD8 ratio varies with the immune dysregulation caused by viral infection." (PMID 35685584, 2022). "This suggests that the possible AaVA-1-CD4 interaction-mediated impact on viral infections may be associated with the direct effect on CD4 protein rather than downstream immune molecule activations." (PMID 36070318, 2022). "In line with previous findings, these results suggest that decreased number of CD4+ helper T cells could diminish the ability to defend against virus infection, such as HIV, making substances more susceptible to HIV infection." (PMID 36238831, 2022).
viral infection (continued). "Our previous studies of FTY720 in primary CD4 T cells demonstrated that the inhibition of infection due to S1P receptor modulation was likely primarily an effect specific to target cells, rendering them less susceptible to incoming virus infection." (PMID 35412343, 2022). "LCMVARM causes an acute viral infection and a well-characterized CD4+ and CD8+ T cell response." (PMID 35440113, 2022). "Adaptative immune responses may influence the risk of viral infections in newborns as their CD4+ T cells have delayed synthesis of IFNγ and IL-2 in presence of viral infections." (PMID 36482106, 2022). "Different T cell subpopulations have distinct characterizations and functions, and we reveal the high heterogeneity of susceptibility to viral infection and biological responses such as apoptosis in various CD4+ T and CD8+ T cell subsets through single-cell transcriptome analyses." (PMID 35317717, 2022). "Higher CD4/CD8 ratios as seen in infants with viral infection in our cohort may also be linked with a potential immaturity state carrying increased infection risk." (PMID 34512621, 2021). "We next examined whether METTL3 deficiency in CD4+ T cells affects GC formation during viral infection." (PMID 33637761, 2021). "We thus believe that the mitochondrial and CD4 T cell dysregulations observed in these virus-controlled PLHIV are caused by either immunologic scarring during early active viral infection or, more likely, by low-grade inflammation during latent viral infection, or both." (PMID 34017335, 2021). "It was also reported to promote CD4 (+) T-cell growth, which may compensate for the loss of CD4 (+) T cells at the time of fatal viral infection." (PMID 34834128, 2021). "Using an adoptive transfer model, we found that METTL3-deficient CD4+ T cells showed a delayed differentiation and a slower proliferation upon acute viral infection, although they were activated normally as shown by expression of the surface markers via both in vivo and in vitro assay." (PMID 33637761, 2021). "In this study, we investigate whether CD47 modulation by HIV-1 Vpu might promote the susceptibility of macrophages to viral infection via phagocytosis of infected CD4+ T cells." (PMID 34425695, 2021). "For example, the model should contain virus susceptible target cells, including CD4+ T lymphocytes, dendritic cells, monocytes and macrophages that display receptors and co-receptors for viral infection and possess the host cell machinery to complete the viral life cycle." (PMID 32650790, 2020). "This could be due to the iatrogenic immunosuppression lowering both CD4+ and CD8+ T cells in the first lymphoma type while the viral infection causes a more pronounced loss of CD4+ than of cytotoxic CD8+ T-cells." (PMID 33344238, 2020). "Some mutations in the CD4 gene are related to immune diseases or viral infection." (PMID 33297958, 2020). "Since CD4 receptors and CCR5 coreceptors are critical for HIV/SIV attachment and entry into target cells, these results suggest that arsenic trioxide might reduce the susceptibility of CD4+ T cells to viral infection during reactivation of latency provirus." (PMID 31380187, 2019). "Factors as leukopenia, medications, advanced liver disease, splenomegaly, viral infections such as Epstein Barr virus, cytomegalovirus, human T-cell leukemia virus 1, and bacterial infections such as tuberculosis can cause the absolute CD4+ T-cell count to decrease." (PMID 30192795, 2018). "Furthermore, inhibition of cdc42, RhoA or Rho-associated protein kinase (ROCK) inhibited viral infection, demonstrating that the appropriate function of Rho family GTPases and their substrates is essential to optimal infection of CD4+ T cells." (PMID 29970186, 2018). "To determine whether ROS can cause DNA damage and cell apoptosis during viral infection, we measured the ROS levels in naïve CD4 T cells isolated from HCV and HS by flow cytometry using the DCFDA, a fluorogenic dye that measures ROS within the cells." (PMID 30185784, 2018).
viral infection (continued). "These differentially expressed miRNAs were found to regulate many common (for B and CD4+ T cells) biological pathways and processes, such as several signaling pathways, viral infection-associated processes, and processes related to regulation of transcriptional activity." (PMID 29381765, 2018). "Active viral infection in T cells in the explants could explain the loss of CD4 T cells in HIV-infected explants." (PMID 30532754, 2018). "However, CD4 T cells are required for establishing sufficient immunity to prevent severe weight loss during primary and secondary viral infections." (PMID 29234060, 2017). "Importantly, salivary gland IL-10+ T cells expressed high levels of the co-stimulatory molecule ICOS that has previously been implicated in the development of IL-10-secreting CD4+ T cells during viral infection." (PMID 27926930, 2016). "In order to explore the importance of CD4+ T cell derived Prf1 for successful host defense in CNS virus infection in vivo, we immunized Prf1 deficient mice (Prf1-/-) with MVA/CFA and established viral encephalitis in CD8+ T cell depleted animals by intrathecal infection with VV." (PMID 24606807, 2014). "Several studies indicated the impairment of TLR signaling after viral infection and incorporation which may assist in the establishment of infection by opportunistic bacteria and fungi, in addition to the loss of CD4+ T cells." (PMID 25121610, 2014). "The alteration of 5 genes (Ctss, H2-Dma, Lgmn, H2-Eb1, and Cd4) in MHC-II-associated pathway by the medium-dose SFXF treatment could potentially prevent virus attachment against viral infection, before virus could replicate and cause infection in host cells." (PMID 24527057, 2014). "We speculate this loss is due to direct viral infection since at least in the gut, these cells express both CD4+ and CCR5+." (PMID 25364618, 2014). "However, epitope-specific CD4+ T cells can be protective or pathogenic depending on when activated T cells are available in conjunction with viral infection." (PMID 22985464, 2012). "However, many acute viral infections, including cytomegalovirus and Epstein Barr virus can be associated with transient lymphocytopenia and CD4+ T lymphocytopenia." (PMID 24893304, 2012). "Combined, these results indicate CD69+CD4+ T cells are a major early target for viral infection, and their rapid loss by direct infection may have profound effects on intestinal immune regulation in HIV infected patients." (PMID 22096538, 2011). "We also found that P. marneffei-activated MDDCs efficiently activated resting CD4+ T cells through cell-cell contact and thereby could result in more susceptible targets for viral infection." (PMID 22110688, 2011). "The targeted loss of CD4+ memory cells occurs in multiple tissues during the acute phase of infection, and this loss, especially affecting cells in gut associated mucosal tissue, strongly impacts the long-term outcome of viral infection." (PMID 22043290, 2011). "Moreover, we found that P. marneffei-stimulated MDDCs efficiently activated resting CD4+ T cells and induced more susceptible targets for viral infection." (PMID 22110688, 2011). "Whether the loss of CD4 cells is a direct consequence of virus infection or bystander apoptosis of uninfected cells is also uncertain." (PMID 21255440, 2011). "Besides contributing to direct or indirect control of active chronic viral infections, virus-specific CD4 T cell responses also bear the potential of causing immunopathology, particularly in case of (abnormally) increased frequencies or in case of defective immune regulation." (PMID 23717308, 2013). "Some studies have also identified cytotoxic CD4+ T lymphocytes, suggesting their potential dual roles in viral infections." (PMID 41430129, 2025). "The CD4/CD8 ratio proved to be an important marker for acute viral infection, positively reflecting the effectiveness of the treatment." (PMID 41157651, 2025).
viral infection (continued). "Bystander activation of CD8+ and CD4+ T cells during acute viral infection, or after vaccination, respectively, is well described." (PMID 40990918, 2025). "MD genetic resistance has been attributed to molecular mechanisms controlling the transcriptional response to MD viral infection using bulk RNA sequencing of immune cells and targeted sequencing of CD4 T cells." (PMID 39880866, 2025). "HIV persists in resting CD4+ primary infected cells, forming a reservoir that is resistant to therapy, and thus a main barrier toward elimination of viral infection." (PMID 40607797, 2025). "During the hyperacute phase of viral infection, the cytokine storm has a significant impact on the destruction of CD4+ T cells and the immune system." (PMID 40757669, 2025). "Contrarily, the intramuscular CD4 T-cells are increased in both young and aged mice during a viral infection, whereas the number of intramuscular CD8 T-cells increased only in aged muscle." (PMID 40373032, 2025). "This study evaluated the value of T lymphocyte subsets in predicting viral infection through ROC curve analysis, revealing that the CD4+/CD8+ ratio demonstrated moderate discriminatory capacity." (PMID 41448851, 2025). "In humans, an increased amount of CD4+/CD8+ T cells has been observed in cases of viral infection and chronic disease." (PMID 40316897, 2025). "Taken together, although NK cell-mediated deletion of CD4+ T cells prolongs the chronicity of infection, it also limits the development of autoimmunity in response to viral infections." (PMID 40255388, 2025). "On the other hand, Ikaros zinc finger transcription factor Eos (Ikzf4) is a positive regulator of CD4+CTLs during viral infections, such as influenza A virus (IAV) infection." (PMID 41009359, 2025). "Protection of target cells from viral infection, maintenance of CD4+ T cell homeostasis, and support of alternative cell types to helper functions contribute to minimize the impact of viral infection on immune system functionality." (PMID 39842407, 2025). "Along with the T CD4+ cells, the presence of cytotoxic T CD8+ lymphocytes, as seen in our model, is commonly associated with viral infections and found to be increased in patients with severe encephalitis." (PMID 39907280, 2025). "Our results demonstrate that CD6 acts as a negative regulator of CD4 T cell activation in CNS draining cLN following virus infection." (PMID 39679790, 2025). "Following acute viral infection, naïve CD4+ T cells differentiate into T follicular helper (Tfh) and T helper 1 (Th1) cells that generate long-lived memory cells." (PMID 39677644, 2025). "The change in CD4+ and CD8+ is noteworthy since a high CD4/CD8 ratio can be caused by various factors, most notably acute viral infections." (PMID 40422255, 2025). "At diagnosis, PLWH with Non-R5 viral infections exhibited lower CD4+ T cell count (329.02 cells/μL) compared to those with R5 viruses (431.82 cells/μL), remained above 200 cells/μL." (PMID 41409299, 2025). "The CD4+ T cells are also known to succumb to exhaustion in such chronic viral infections, which can further weaken the anti-viral CD8+ T cell responses." (PMID 40872312, 2025). "CD4+ T cells or B cells play an important role in ultimately clearing the virus and preventing viral infection." (PMID 40977416, 2025). "On the other hand, the dual roles of TCF1 in CD4+ TM cell differentiation and Tfh polarization make it an unreliable marker for memory precursors during Th1/Tfh response under viral infections." (PMID 40391228, 2025). "In contrast to inducible immune cell targets, CD4 expression exhibits only minor variations following antigenic activation, virus infection or epigenetic regulation during thymic differentiation, thereby enabling accurate quantification of CD4+ cells by PET." (PMID 40561008, 2025).
viral infection (continued). "CXCR3 directs the migration of activated CD4+ T cells to interfollicular region of LNs, which is strongly correlated with increased Th1 effector differentiation under viral infection." (PMID 40391228, 2025). "The terminal differentiation of cytotoxic CD4+ T cells has been described in autoinflammatory disease, the tumor microenvironment, and chronic (or latent) viral infection." (PMID 40214640, 2025). "This was performed to simulate the gene expression changes in CD4+ T cells following viral infection, designating this modified group as “perturbed CD4+ T cells”." (PMID 39948393, 2025). "In one sense, effector CD4+ T lymphocytes are major components of the immune response to chronic viral infections; however, some subtypes of natural killer cells selectively eliminate effector CD4+ T cells, which in turn reduces autoimmune responses." (PMID 40255388, 2025). "CD4 + T cells provide critical help to CD8+ T cells during acute viral infection to generate CD8+ T cell memory and, during persistent viral infection, maintain CD8+ T cell functionality." (PMID 41409145, 2025). "The CD4+/CD8+ ratio demonstrates only moderate ability to indicate viral infection, suggesting limited value for independent clinical decision‐making." (PMID 41448851, 2025). "Such multifunctional IL-21+IFN-γ+ Tfh CD4+ cells have previously been described as mediators of immune response in spontaneous autoimmune diseases (e.g., lupus and peripheral neuropathy) and viral infections." (PMID 40626363, 2025). "CD4+ CTL were also found in the peripheral blood of patients suffering from various viral infections, autoimmune diseases, or cancer where CD4+ T cells are exposed to antigens over a longer period of time." (PMID 40939292, 2025). "We first evaluated the kinetics and differentiation of polyclonal antigen-specific CD4+ T cells following adjuvanted protein immunization or acute viral infection." (PMID 39283916, 2024). "Studies show that younger individuals have higher baseline T cell activity, including cytotoxic CD8+ T cells and helper CD4+ T cells, which play a crucial role in clearing viral infections." (PMID 39768950, 2024). "The IFNAR has emerged as an essential receptor for RBC alloimmunization (both CD4+ T cell dependent and independent), both at baseline and when enhanced by inflammation (viral infection or lupus-like pathology)." (PMID 38618959, 2024). "Studies have shown that during viral infection, infection with CD4 + T cells is an effective mechanism for the virus to evade the immune response." (PMID 38600309, 2024). "CD4+ Th cell polarization has repeatedly demonstrated its importance during the development of viral diseases, serving as coordinator of either cellular or humoral immune responses." (PMID 39257580, 2024). "CD4+ T cells that are generated in response to viral infection produce a substantial amount of IFN-γ and are designated as a Th1-type phenotype." (PMID 39066362, 2024). "For example, alum, commonly used in licensed subunit vaccines, tends to promote strong antibody responses crucial for viral infection prevention but elicits relatively weak CD4+ T cell responses which are generally Th2-biased." (PMID 38712080, 2024). "CD4+ CTLs are well characterized as key players in multiple tumors, viral infections, and some autoimmune diseases." (PMID 38499993, 2024). "Those with any T-lymphocyte CD4 count < 200 cells/mm3 had a 53% (aOR:0.47, 95%CI: 0.26–0.84; p = 0.011) lower chance of being adequately vaccinated with the yellow fever vaccine when compared to individuals with all counts > 350 cells/mm3." (PMID 39340033, 2024). "We found that chronic virus infection not only diminished the pool of pre-existing Lm-OVA specific CD4+ and CD8+ Tm cells, but also impaired their capacity to produce effector cytokines as well as mount recall responses." (PMID 38547316, 2024).